TLR7 (toll like receptor 7)
Diseases named in the same sentence as TLR7 in open-access papers (continued):
Sharing a sentence is not in itself a finding about the gene and the disease.
Obesity (15 papers, 2019 to 2024). Accumulation of substantial excess body fat. "The contribution of TLR3 and TLR7 to obesity-mediated pathogenesis was established when their deficiencies were shown to restore glucose tolerance, decrease metabolic inflammation and ameliorate NAFLD in HFD fed animals." (PMID 33574823, 2020). "TLR3 and TLR7 KOs were found to be protective against HFD induced obesity and weight gain and IL1a-KO reduces adiposity, which reflects predicted gene changes in CR20-HFD males compared to FED-HFD." (PMID 38720938, 2023). "The TLR7 expression in adipose tissues is upregulated in human obesity, and is reduced after bariatric surgery." (PMID 35955609, 2022). "Of note, the TLR7−/−-mice exhibit less metabolic inflammation and improved glucose tolerance in murine models of diet-induced obesity." (PMID 35955609, 2022). "Originally interpreted to be a pattern-recognition receptor (PRR) sensing foreign nucleic acids, TLR7 has recently been proposed to recognize physiological ligands as well, in particular cell-free nucleic acids (cfDNA), which are increased in human obesity." (PMID 35955609, 2022). "While we recently demonstrated a significant expression of functional TLR9 in adipocytes, only sparse data are available on the overall expression of TLR7 in adipocytes in obesity." (PMID 35955609, 2022). "Overall, TLR8ko pDCs and cDCs have higher TLR7 expression than WT cells, whereas HFD-mediated obesity leads to an increase of TLR7+TNF+ pDCs and cDCs, and this is more profound in TLR8ko than in WT mice." (PMID 31552019, 2019). "In conclusion, our data demonstrate that HFD-induced obesity increases TLR7 expression and signaling, that contributes to the acceleration of the progression of SLE and metabolic abnormalities." (PMID 31552019, 2019). "This concept is supported by evidence that several inflammatory RBPs, including TLR3, TLR7, and PKR, are involved in the induction of obesity-associated chronic inflammation." (PMID 31482095, 2019). "TLR7 expression in subcutaneous adipose tissues is upregulated in human obesity, followed by increased expression of MyD88 and IRAK1 and may also contribute to features of MetS." (PMID 38346802, 2024). "Thus, TLR7 has been proposed to play a significant role in metabolically induced inflammation in obesity." (PMID 35955609, 2022). "Our data further show that TLR3/TLR9 expression was associated independently with the expression of SRA1 in individuals with T2D, while TLR3, TLR7 and IRAK1 were identified as the independent predictors of adipose SRA1 expression in individuals with obesity." (PMID 36552771, 2022). "AT-SRA1 expression was independently predicted by TLR3/TLR7 and IRAK1 in those with obesity and by TLR3/TLR9 in individuals with T2D." (PMID 36552771, 2022). "Both TLR7 and TLR9 sense nucleic acids and have been postulated to participate in metabolically induced inflammation in the context of obesity and insulin resistance." (PMID 35955609, 2022). "In individuals with obesity (N = 64), TLR3, TLR7 and IRAK1 were detected as the independent predictors of adipose SRA1 expression." (PMID 36552771, 2022). "Our data show strong positive correlations between adipose IRF5 gene expression and that of TLR2, TLR7, TLR8, TLR9, MyD88, IRAK-1, and IRF3 in obesity." (PMID 31718015, 2019). "Furthermore, TLR3/TLR7/IRAK1 and TLR3/TLR9 were identified as independent predictors of AT SRA1 expression in individuals with obesity and T2D, respectively." (PMID 36552771, 2022). "The implication of TLR7 in the chronic inflammation of SLE in the context of obesity or metabolic syndrome has never been reported to date." (PMID 31552019, 2019). "In obesity, dynamic alterations in modification and localization of RNAs appear to modulate the RNA-RBP networks and activate proinflammatory RBPs, such as double-stranded RNA (dsRNA)-dependent protein kinase (PKR), Toll-like receptor (TLR) 3 and TLR7, and RNA silencing machinery." (PMID 31482095, 2019).
Obesity (continued). "When assessing the placental expression of factors related to viral recognition (TLR3, TLR7, and IRF3) and antiviral response (IFNs I and III, STING, RIG-I, MxA, and ISG15) from parturient with pregestational obesity (BMI ≥ 25), no changes were detected between the obese and non-obese samples." (PMID 36851534, 2023).
actinic keratosis (14 papers, 2015 to 2024). A precancerous lesion of the skin composed of atypical keratinocytes. "Imiquimod (IMQ), a Toll-like receptor 7 (TLR-7) agonist, was used to treat actinic keratosis (AK) and superficial basal cell carcinoma (BCC)." (PMID 36388459, 2022). "Aldara is cream containing the Toll-like receptor 7 agonist imiquimod approved for actinic keratosis, BCCs, and precancerous SCCs (SCC in situ), but not recommended for the treatment of advanced SCCs." (PMID 36581625, 2022).
colitis (13 papers, 2016 to 2026). Inflammation of the colon. "Our data demonstrate that ATG16L1-deficiency in DCs promotes the development of LP CD8+ TRM cells and increases susceptibility to colitis which can be attenuated by stimulation of the TLR7 signaling pathway." (PMID 39464882, 2024). "Our data demonstrate that ATG16L1-deficiency in myeloid and dendritic cells leads to an increase in LP TRM and consequently to increased susceptibility to colitis by impairing the recognition of enteric viruses by TLR7." (PMID 39464882, 2024). "Mice pre-treated with the TLR3 agonist poly(I:C) and the TLR7 agonist, imiquimod, were protected from DSS-induced colitis, whereas mice deficient in both TLR3 and TLR7 were more susceptible to DSS-induced colitis." (PMID 37191444, 2023). "Furthermore, Tlr7-/- and Atg16l1ΔCd11c mice were more susceptible to dextran sulfate sodium colitis with an increase in disease activity index, histoscore, and increased secretion of IFN-γ and TNF-α." (PMID 39464882, 2024). "Consequently, our data demonstrate that ATG16L1-deficiency in myeloid cells promotes LP TRM cell accumulation and increases the susceptibility to colitis by impairing the activation of TLR7 signaling in response to RNA viruses." (PMID 39464882, 2024). "Based on our observation of an accumulation of LP TRM cells, we hypothesized that Tlr7-/- mice are more susceptible to acute colitis." (PMID 39464882, 2024). "For instance, the TLR7 agonist Imiquimod significantly alleviates dextran sodium sulfate (DSS)-induced colitis in mice by inducing the expression of type IFN and antimicrobial peptides." (PMID 41495287, 2026). "The TLR7 agonist Imiquimod alleviates DSS-induced colitis in mice by inducing the expression of type I interferons (IFN) and antimicrobial peptides (AMPs) and inhibits the survival of intracellular pathogens such as Salmonella." (PMID 41495287, 2026). "ATG16L1-deficieny in myeloid cells or DCs resulted in a similar phenotype than Tlr7-/- mice, with increased susceptibility to DSS colitis, increased disease activity index, histoscores, and increased secretion of IFN-γ and TNF-α." (PMID 39464882, 2024). "In conclusion, we demonstrated that relation between ATG16L1 and TLR7 plays an important role in maintaining immune response to intestinal viruses and protects against colitis." (PMID 39464882, 2024). "Our findings suggest an important convergence of the ATG16L1 and TLR7 signaling pathways in myeloid cell-mediated immune responses to intestinal viruses and protection against the development of colitis." (PMID 39464882, 2024). "To assess the role of TLR7 signaling in the development of chronic colitis we utilized the chronic DSS colitis model by administering four cycles of DSS drinking water to WT or Tlr7-/- mice." (PMID 39464882, 2024). "Although TLR7 activation has been shown to protect mice from DSS colitis by mediating the action of enteric viruses, its expression in colonic mucosa is increased following antibiotic-induced dysbiosis in mice." (PMID 37047398, 2023). "This protective role of TLR7 is in line with that observed in mice during DSS-induced colitis, where epithelial lesions, clinical signs and serum levels of pro-inflammatory markers were ameliorated after TLR7 stimulation with imiquimod." (PMID 36674770, 2023). "In that study it was also shown that the oral application of combined TLR3 and TLR7 agonists or inactivated rotavirus particles protected mice against DSS-induced colitis." (PMID 29570694, 2018). "Deletion of TLR4, TLR2, TLR5 and TLR9 as well as simultaneous deletion of TLR3 and TLR7 led to disturbed epithelial homeostasis and enhanced susceptibility to acute DSS-induced colitis, however with less severe pathology than in MyD88-deficient mice." (PMID 29570694, 2018). "Our findings reveal that TLR7-deficiency promotes the development of LP CD8+ TRM cells under steady-state condition and exacerbates susceptibility to dextran sulfate sodium (DSS)-induced colitis." (PMID 39464882, 2024).
colitis (continued). "Increased TNF-α secretion observed in Tlr7-/-, Atg16l1Cd11cCre, and Atg16l1Lyz2 mice may contribute to the susceptibility to DSS-induced colitis via its detrimental effects on intestinal epithelial cells." (PMID 39464882, 2024). "It is known that TLR8 activation can enhance TNF and IL-1β production, both associated with mucosal inflammation in UC, whereas TLR7 agonists could induce a type I IFN response and prevent experimental colitis in mice." (PMID 37446274, 2023). "Similarly, administration of individual synthetic ligands for TLR3, TLR7 and TLR9 had protective effects against colitis in mice, which were also associated with the induction of type I IFNs." (PMID 29570694, 2018). "Similarly, to the phenotype we observed in Tlr7-/- mice, myeloid- and DC-specific deletion of ATG16L1 (Atg16l1ΔLyz2 and Atg16l1ΔCd11c mice) resulted also in elevated LP CD8+ TRM cells and increased susceptibility to DSS colitis." (PMID 39464882, 2024). "The increase of intestinal inflammation in Tlr7-/- mice correlated with an increase in granzyme B+ CD8+ TRM cells, IFN-γ, and TNF-α secretion during DSS colitis and suggest that CD8+ TRM cells contribute to the increased susceptibility seen in Tlr7-/- mice." (PMID 39464882, 2024). "The TLR7 agonist imiquimod, administered orally, induces type-1 IFN responses in the colonic mucosa to ameliorate DSS colitis and has effects in vitro on antimicrobial peptide production." (PMID 29515999, 2018). "Lack of TLR3 and TLR7 during DSS colitis abrogated IFN-β production of colonic pDCs in response to TLR3/7 agonists indicating that type I IFN produced by pDCs may be important to counterregulate inflammation in the colon." (PMID 29570694, 2018). "DSS-treatment for 8 days resulted in elevated mRNA levels of TLR4 and TLR7, while expression of TLR2 and TLR9 did not change in colitis mice." (PMID 27658624, 2016).
dengue (13 papers, 2008 to 2025). "In the present study, heterozygous genotypes of TLR9 (rs187084, rs5743836) and of TLR7 (rs179008, rs179009) were found to be significantly associated with dengue cases as compared to controls." (PMID 34113509, 2021). "In the same way, the TLR7-rs3853839-C/C genotype has been demonstrated to have a significant association with dengue infectivity in Indian patients." (PMID 33138336, 2020). "In a previous study, a differentially expressed TLR profile was reported in children with severe dengue, wherein increased expression of TLR7 and TLR4 transcript variant 3 (TLR4R3) and decreased expression of TLR1, TLR2, TLR4R4, and TLR4 cofactor CD14 were observed." (PMID 34603272, 2021). "Differentiation of classical to intermediate monocytes has been documented in dengue virus infections in humans, as well as when using TLR-7/8 adjuvants in RMs." (PMID 34266981, 2021). "The present study demonstrates that mutants of TLR3 rs3775291 and heterozygous genotypes of TLR7 and TLR9 are associated with susceptibility of dengue virus infection." (PMID 34113509, 2021). "The allelic and genotypic frequencies followed the Hardy Weinberg equilibrium, with the exception of TLR7-rs3853839 for the dengue (DEN) group." (PMID 33138336, 2020). "TLR-3 and TLR-7 have been reported to play important roles in inhibiting dengue virus infection in U937 and HEK293 cells, respectively." (PMID 21200427, 2010). "Mutant allele of TLR7 and TLR9 was significantly associated with dengue." (PMID 34113509, 2021). "Altogether, our results imply that immature particles, as a carrier to endolysosome-localized TLR7 sensor, may contribute to regulate the progression of dengue disease by eliciting a strong innate response." (PMID 25340500, 2014). "In summary, Toll-like receptors such as TLR3, TLR7, and TLR8 play significant roles in the innate immune response against dengue virus infection." (PMID 37631896, 2023). "TLR7 and TLR8 are capable of recognizing single-stranded RNA, which is another form of viral RNA produced during the dengue virus infection." (PMID 37631896, 2023). "The mRNA for several innate receptors was increased following dengue virus plus dengue-immune sera treatment, including PKR, RIG-I, MDA5, TLR3 and TLR7." (PMID 22479521, 2012). "When we compared the acute samples with the samples collected at convalescence in our dengue positive patients we saw an up regulation of TLR7 and IRF7 which indicates an activation of the TLR7 signalling pathway." (PMID 21810247, 2011). "However, whilst TLR2 expression significantly increased in IM and NM subsets from acute dengue patients, TLR7 was not." (PMID 40934228, 2025). "Interestingly, many of the responses seen in acute dengue in relation to the convalescent baseline were replicated when comparing to other non-dengue febrile illnesses, indicating a more prominent IFN-response, specific to dengue disease, and a selective utlization of TLR7, MDA5 and OAS." (PMID 21810247, 2011).
Alzheimer disease (12 papers, 2014 to 2025). A progressive, neurodegenerative disease characterized by loss of function and death of nerve cells in several areas of the brain leading to loss of cognitive function such as memory and language. "TLR7 and neuronal apoptosis are implicated in other neurodegenerative diseases, including Alzheimer’s disease." (PMID 33806288, 2021). "TRAIL signaling downstream of TLR7 activation may mediate neuronal apoptosis and could be associated with neurological diseases, including ischemic stroke, Alzheimer's disease, and multiple sclerosis." (PMID 38340139, 2024). "Besides the TLR/TNFα/apoptosis/necroptosis pathway as a driver of neurodegeneration in Alzheimer’s disease, we identified a distinct TLR7/IL-6/apoptosis axis in viral neural pathogenesis mediated by TLR7 upon EV71 infection in vivo." (PMID 31730654, 2019). "Let-7 isoforms have been shown to be increased in the cerebrospinal fluid of patients with Alzheimer’s disease, further suggesting that let-7/TLR7/TRAIL signaling could be involved in multiple neurodegenerative disorders and represent a useful therapeutic target." (PMID 33806288, 2021). "For instance, the secreted miRNA let-7 can directly target Toll-like receptor 7 (TLR7) by acting as its ligand, thereby activating TLR signaling transduction pathways and inducing an immune response in Alzheimer’s disease." (PMID 39188306, 2024). "Intriguingly, a recent paper indicates a potential new function of HERV-K transcripts in neurodegeneration, via trigger TLR7 and TLR8 signaling in a mouse model of Alzheimer’s disease." (PMID 36451209, 2022). "This study is focused on the potential roles of various TLRs in various neurodegenerative diseases such as Parkinson’s disease (PD) and Alzheimer’s disease (AD), namely TLR2, TLR3, TLR4, TLR7, and TLR9 in AD and PD in human beings and a mouse model." (PMID 34827372, 2021). "Here again, both beneficial and detrimental roles were attributed to TLRs and for instance TLR7, TLR8 and TLR9 signaling could enhance microglial amyloid beta uptake in the early stage of Alzheimer’s disease, but over time contribute to sustained neuroinflammation." (PMID 34335238, 2021). "Emerging evidence suggests that beyond its function as an immune receptor in immune cells, TLR7 also serves as a death receptor in various forms of non-infectious central nervous system (CNS) injury, such as ischemic stroke, Alzheimer’s disease, and morphine-mediated neurodegeneration." (PMID 31730654, 2019).
diabetes (12 papers, 2014 to 2025). "Female TLR7-deficient NOD mice started developing diabetes at the age of 15 weeks, while male TLR7-deficient NOD mice did not develop diabetes." (PMID 36389822, 2022). "In line with the in vitro coculture results, the Tlr7-deficient B cells significantly delayed the diabetes development induced by diabetogenic CD4+ T cells in the Rag−/− NOD recipients." (PMID 33432061, 2021). "We demonstrated that Tlr7 deficiency suppresses the development of diabetes by altering predominantly B-cell development, differentiation, and functions." (PMID 33432061, 2021). "The TLR7/8 activation of the downstream immune system and auto-immune risk phenotype contributes to beta-cell destruction, promotes diabetes development, and causes T-cell exhaustion." (PMID 32296701, 2020). "This study aims to investigate the effects of hyperglycemia on the gene and protein expression of CD36, CD69, CD274, and TLR-7 during wound healing using a rat model of induced diabetes." (PMID 41465460, 2025). "The mechanism shows that B cells from (Tlr7−/−) NOD mice suppress the CD4+ T-cell response to diabetes, protecting immunodeficient NOD mice from diabetes induced by diabetogenic T cells." (PMID 39776900, 2024). "In accordance with the reduction in diabetes development, female Tlr7−/− NOD mice displayed significantly less insulitis than their female Tlr7+/+ NOD counterparts." (PMID 33432061, 2021). "T1D developed in most of both female and male WT NOD mice, but only male Tlr7 KO mice were protected from T1D with 16 of 17 Tlr7 KO male NOD mice diabetes free at 30 weeks." (PMID 33322152, 2020). "However, in chronic conditions like diabetes, elevated TLR-7 expression is linked to impaired healing, and stimulating TLR-7 with agonists has been shown to delay healing by prolonging inflammation, as seen in models of chronic wounds." (PMID 41465460, 2025). "To further test if Tlr7-deficient B cells attenuate diabetes development, we adoptively transferred Tlr7-deficient or Tlr7-sufficient B cells together with purified CD4+ T cells (Tlr7 sufficient) from diabetic NOD mice into immunodeficient Rag−/− NOD recipients." (PMID 33432061, 2021). "Although TLR7 has been implicated in the bystander activation, the melanoma differentiation-associated protein 5 (MDA5), might also have a role in rotavirus-induced type-I IFN expression, and thus diabetes progression." (PMID 31430946, 2019). "Thus, we hypothesise that environmental factors (e.g. virus) in predisposed and/or autoantibody-positive individuals stimulate dysregulated 2′-5′ pathway through toll-like receptor 7 and type 1 IFN in the innate immune system, causing inflammation in the islets and progression to diabetes." (PMID 33973017, 2021). "Of particular importance is the heightened expression of the TLR7 protein in CD19+CD138+ islet B cells, which encompass a substantial proportion of the B cell population in the pancreas during the development and onset of diabetes in NOD mice." (PMID 36508037, 2023). "Moreover, Tlr7−/− NOD B cells were found to suppress diabetogenic CD4+ T-cell responses and protect immunodeficient NOD mice from developing diabetes induced by diabetogenic T cells." (PMID 33432061, 2021). "Here, rotavirus stimulation of splenocytes from diabetes-prone NOD mice was shown to induce APC and B cell activation, which was prevented by VP7 blockade, inhibition of endosomal acidification and interference with TLR7 or IFNAR signaling." (PMID 24676425, 2014).